SOCS1 (suppressor of cytokine signaling 1)
Diseases named in the same sentence as SOCS1 in open-access papers (continued):
Sharing a sentence is not in itself a finding about the gene and the disease.
prostate carcinoma (24 papers, 2012 to 2026). A carcinoma that arises from epithelial cells of the prostate gland. "As miR-221-5p is able to promote migration of prostate cancers, the association of miR-221-5p/SOCS1 with metastasis and EMT need to be addressed in the future." (PMID 29506516, 2018). "In prostate cancer (PCa), elevated expression of miR-30d that targets SOCS1 mRNA is associated with increased risk of disease recurrence." (PMID 28235401, 2017). "Reduced expression or mutations in SOCS1 and SOCS3 have been associated with sustained STAT3 activation, accelerating the progression of pancreatic ductal adenocarcinoma, prostate cancer, and glioblastoma." (PMID 40166646, 2025). "The SOCS1 mimetic peptide Tkip has been shown to inhibit prostate cancer growth in vitro, indicating the potential utility of SOCS1-mediated inhibition in tumor growth control." (PMID 38415248, 2024). "Suppression of let-7b-5p is conducive to an anti-tumorigenic macrophage phenotype in prostate cancer by SOCS1/STAT pathway." (PMID 37019900, 2023). "The SOCS1/STAT1 pathway played a critical role in inhibiting the growth of prostate cancer by regulating macrophage polarization in the tumor microenvironment." (PMID 35600340, 2022). "MiR‐210‐3p promotes EMT and bone metastasis thorough NF‐κB signaling by targeting TNPI1 and SOCS1 in prostate cancer." (PMID 33939301, 2021). "It has been reported that hsa-miR-221-5p regulates the proliferation and metastasis of prostate cancer cells by targeting the expression of the suppressor of cytokine signaling 1 (SOCS1) gene." (PMID 32120850, 2020). "On the other hand, in solid cancers where STAT5 plays a causal role such as liver and prostate cancer, in addition to SOCS3, SOCS1 is frequently inactivated and mouse models of SOCS1 ablation increase both liver and prostate tumorigenesis." (PMID 31557897, 2019). "SOCS1 as a tumor suppressor gene has been reported in previous researches, and found that SOCS1 has a lower expression level in patients with prostate cancer tissues than adjacent tissues." (PMID 29506516, 2018). "And we also confirm that miR-221-5p enhances cell proliferation and metastasis through post-transcriptional regulation of SOCS1 by vitro and vivo experiments in human prostate cancer." (PMID 29506516, 2018). "Our studies have provided evidence that miR-221-5p can inhibit the expression of SOCS1 to control tumor proliferation, migration and tumorigenicity of prostate cancer cells both in vitro and in vivo." (PMID 29506516, 2018). "In this study, we investigated the potential functions of miR-221-5p in prostate cancer and found that miR-221-5p can specific target SOCS1 (Suppressers of cytokine signaling (SOCS) family protein, which is tumor suppressor genes." (PMID 29506516, 2018). "A number of studies have shown that SOCS1 attenuates growth of prostate cancer cells in vitro and in vivo." (PMID 28235401, 2017). "In prostate cancer, SOCS1 expression decreases after androgen-deprivation treatments and is elevated in recurrent patients to inhibit cell proliferation." (PMID 28228755, 2017). "In conclusion, we find a new miR-221-5p/SOCS1 pair that may play an important role in progression of prostate cancer." (PMID 29506516, 2018). "Given that the expression of SOCS1 is regulated at post-transcriptional level by miR-221-5p, detection the expression of miR-221-5p in cancer tissues would discover an effective approach to evaluate miR-221-5p as a potential prostate cancer biomarker." (PMID 29506516, 2018). "Future studies are needed to explore the association with miR-221-5p and SOCS1, and whether miR-221-5p/SOCS1 pair can be used as a new biomarker to diagnosis of prostate cancer, and whether it can be as a novel therapeutic target in prostate cancer treatment." (PMID 29506516, 2018). "The levels of SOCS1 mRNA and protein were significantly down-regulated in prostate cancer tissues." (PMID 23231923, 2012).
prostate carcinoma (continued). "Studies have shown that miR-210-3p maintains the continuous activation of NF-κB signaling by targeting TNIP1 and SOCS1 and leads to EMT and invasion of prostate cancer cells." (PMID 34853307, 2021). "In prostate cancer, miR-210-3p maintains the activation of NF-κB signaling via targeting TNIP1 and SOCS1, resulting in EMT, invasion, migration, and bone metastasis of tumor cells." (PMID 32908121, 2020). "A previous study showed that, miR-210-3p directly binds SOCS1 and TNIP1 through activating NF-κB pathway in prostate cancer cells, resulting in bone metastasis progression of prostate cancer." (PMID 31528235, 2019). "Additionally, SOCS1 suppresses the expression of CDK2 and 4, along with cell cycle regulatory proteins such as cyclin D1 and cyclin E, thereby inhibiting prostate cancer growth and metastasis." (PMID 40166646, 2025). "Similarly, by targeting suppressor of cytokine signaling 1 (SOCS1) and TNIP1, miR-210 indirectly activates the NF-κB pathway, which promotes prostate cancer progression and metastasis." (PMID 39634266, 2024). "It was found that miR-221 could regulate SOCS1 expression through targeting its 3′UTR, thus promoting proliferation and migration of prostate cancer cells in vitro and facilitating tumorigenesis in vivo." (PMID 31728180, 2019). "Another study indicated that let‐7b‐5p may regulate M2 polarization through the SOCS1/STAT pathway and that let‐7b‐5p inhibitors reverse M2 differentiation while enhancing macrophage phagocytic activity, ultimately suppressing prostate cancer cell proliferation." (PMID 41551936, 2026). "Particularly, SOCS1 and SOCS3 have been postulated as candidates to regulate the radio and chemoresistance acquisition in other types of cancer, such as prostate cancer, or cervix cancer, but there is a lack of studies regarding the role of SOCS1 and SOCS3 in radiotherapy resistance in GBM." (PMID 30811476, 2019).
lupus (23 papers, 2009 to 2026). "This case report details a 6-year-old Han Chinese girl diagnosed with Systemic Lupus Erythematosus (SLE) associated with a frameshift variant in the SOCS1 gene." (PMID 40755921, 2025). "In murine models, SOCS1 insufficiency or complete loss-of-function mutations induce lupus-like phenotypes, including autoantibody production, glomerulonephritis, and lymphoproliferation." (PMID 40755921, 2025). "The therapeutic potential of SOCS1-KIR in modulating lupus-associated pathologies has been recently evaluated in Fas-deficient MRL/lpr mice." (PMID 38022642, 2023). "SOCS1 HI was recently identified as a rare cause of multisystem autoimmunity in a small group of patients presenting notably with systemic lupus erythematosus or autoimmune cytopenia." (PMID 37156989, 2023). "Altered SOCS1 expression has been observed in patients with systemic lupus erythematosus and rheumatoid arthritis, with SOCS1 polymorphisms demonstrated to predict severity of the latter disease." (PMID 34604264, 2021). "Treg-specific SOCS1-deficient mice also developed lupus-like phenotypes that are less serious than those in T cell-specific SOCS1-deficient mice, and many adult SOCS1+/− mice exhibited lupus-like manifestations as well." (PMID 29085365, 2017). "Variants of differing penetrance in SOCS1 are associated with clinical constellations consistent with diseases ranging from atopic disorders, systemic autoimmune diseases such as systemic lupus erythematosus, Sjögren syndrome, and rheumatoid arthritis, to a monogenic phenotype." (PMID 40282361, 2025). "Since anti-DNA IgG production is a common clinical immunopathology associated with lupus progression, we next analyzed the correlation between anti-DNA IgG production and SOCS1-KIR mediated leukocyte changes using the 1:1000, 1:3000, and 1:9000 serum dilutions." (PMID 33737712, 2021). "Moreover, it has been reported that SOCS1 is downregulated in glomerular mesangial cells and tubular epithelial cells in lupus mice, and inadequate induction of SOCS1 causes kidney damage via enhanced IFN responses in mice." (PMID 31130957, 2019). "The roles of SOCS1 deficiency in systemic lupus erythematosus (SLE)." (PMID 29085365, 2017). "Moreover SOCS1 deficiency has been implicated in lupus progression, and increased susceptibility to LPS mediated endotoxemia." (PMID 24391643, 2013). "This postulation is further supported by a previous study demonstrating the inhibition of TNFα by SOCS1-KIR in the mrl/lpr rodent model of lupus." (PMID 39867889, 2024). "In previous reports of SOCS1 HI, lupus-like manifestations were ascribed to hyperactivation of the JAK-STAT pathway downstream type I or type II interferons." (PMID 37156989, 2023). "In this study, we show that administration of peptide variants of SOCS1-KIR to MRL/lpr mice mitigated skin lesions, lymphadenopathy, anti-dsDNA IgG levels, and reduced lupus associated kidney pathology." (PMID 33737712, 2021). "Since IFN-γ production is associated with lupus progression and it is modulated by endogenous SOCS112,49,50, we next assessed IFN-γ production following incubation with SOCS1 mimetic or antagonist peptides." (PMID 33737712, 2021). "Although there is good evidence in rodent studies denoting a role for SOCS1 expression in the prevention of murine lupus, more studies are necessary to establish the translational value of this finding." (PMID 24391643, 2013). "Additionally, we have previously shown that the peritoneal injection of SOCS1-KIR into a rodent model of SOCS1 genetic deficiency, or spontaneous lupus model, decreased circulating memory T cells and increased Foxp3 high T lymphocytes." (PMID 35505065, 2022). "Additionally, altered expression of SOCS1 contributes to the progression of chronic inflammatory diseases, such as rheumatoid arthritis, systemic lupus erythematosus, and renal injury." (PMID 23091595, 2012).
lupus (continued). "Aberrations in SOCS1 also contribute to lupus nephritis, a grave complication of SLE, influencing organ performance in regions like the skin, central nervous system, heart, and kidneys." (PMID 38022642, 2023). "Reduced SOCS1 expression in individuals with systemic lupus erythematosus (SLE) and in lupus mouse models is established." (PMID 38022642, 2023). "Using Fas deficient, MRL/MpJ-Faslpr/J (MRL/lpr) mice, which develop lupus-like disease spontaneously, we tested the hypothesis that a peptide mimic of the SOCS1 kinase inhibitory region (SOCS1-KIR) would inhibit lymphocyte activation and modulate lupus-associated pathologies." (PMID 33737712, 2021). "Lupus nephritis is one of the most serious complications of SLE, and it correlates with suppressed SOCS1 signals in renal tissues." (PMID 29085365, 2017). "Patients with active SLE have lower expression of SOCS1 mRNA as compared to patients with inactive SLE, hence indicating that mRNA expression of SOCS1 is negatively correlated with lupus disease activity." (PMID 29085365, 2017). "Over the last few decades, microRNA-155 (miR-155) has emerged as a key proinflammatory regulator in clinical and experimental arthritis and in systemic lupus erythematosus (SLE), targeting specific mRNAs, such as PU.1, SOCS-1, TAB-2, and c-Maf." (PMID 38542233, 2024). "In lupus-prone (NZB × NZW) F1 mice, SOCS1 expression was decreased, whereas pSTAT1 was increased in spleen-derived lymphocytes, thus mirroring the results of SOCS1 expression in peripheral blood mononuclear cells of patients with SLE." (PMID 29085365, 2017). "Recent studies have demonstrated that SOCS1 expression is decreased in patients with SLE and in murine lupus models, and this negatively correlates with the magnitude of inflammation." (PMID 29085365, 2017). "d-Form ALW peptide also ameliorates SOCS1 signals in anti-dsDNA IgG-treated SCID mice, which display glomerular IgG deposition and lupus-like renal damage." (PMID 28620377, 2017). "Insufficiency of SOCS1 expression and abnormalities in cytokine production are prominent in patients with SLE and in murine lupus models." (PMID 29085365, 2017). "Moreover, in different murine models of SLE, SOCS1 suppression contributes to the progression of lupus disease." (PMID 28620377, 2017). "Moreover, the administration of a tolerogenic peptide, hCDR1, prevented lupus onset in NZB/W mice and enhanced production of SOCS1." (PMID 24391643, 2013).
lymphoma (23 papers, 2012 to 2025). A malignant (clonal) proliferation of B- lymphocytes or T- lymphocytes which involves the lymph nodes, bone marrow and/or extranodal sites. "Heterozygous germline SOCS1 variants were previously linked to severe autoimmunity with aberrant lymphoproliferation and transition to lymphomas in some cases." (PMID 37495858, 2023). "In comparison to the distribution of SOCS1 mutations in other lymphomas, point mutations in cHL showed a higher prevalence in the SH3 domain, whereas deletions predominantly affected the JAK Kinase Domain." (PMID 26336985, 2015). "Suppressor of cytokine signaling 1 (SOCS1) mutations have been described in specific sets of malignant lymphomas." (PMID 26336985, 2015). "Given that frequencies and patterns are compatible with other hypermutated genes, our findings support the notion that germinal-center experienced lymphomas are prone to acquire SOCS1 gene mutations by somatic hypermutation." (PMID 23296022, 2013). "Moreover, mutations of SOCS-1 that abolished its binding to JAK3 reinforced the aggressive course of the lymphoma." (PMID 34948183, 2021). "Deletion mutations and functionally defective missense mutations of the SOCS1 gene have been reported in many lymphomas, including Burkitt lymphoma and Hodgkin’s lymphoma.87–89) SOCS1 deficiency is thought to result in the strong activation of JAK, which causes cell proliferation." (PMID 34121041, 2021). "Using this model we reveal a two-step mutational process reflecting disease progression, whereby an activating JAK3 mutation known to drive lymphoma formation is joined in progressed disease by novel inactivating mutations of SOCS1, thereby weakening the latter's inhibitory potency." (PMID 27144517, 2016). "Thus, we show that not only cHL cell lines, but also SOCS1 mutated HRS cells in lymphoma tissue express the mutant allele." (PMID 26336985, 2015). "The skin lesions developed into an aggressive lymphoma characterized by the progression of rapid growing, ulcerating tumors with a CD8+ cytotoxic and γ/δ phenotype with CD30− transformation and SOCS1 mutation." (PMID 39091627, 2024). "In lymphomas, there is evidence of DNA hypermethylation affecting the SOCS1 gene, which in turn can promote cell proliferation by enhancing JAK2 activity." (PMID 37664523, 2023). "Bioinformatic loss-of-function predictions were additionally corroborated by two samples carrying multiple non-synonymous SNVs and matched previously suggested tumor suppressive properties of SOCS1 in lymphoma." (PMID 37495858, 2023). "Several targets of miRNA-155 have been identified in recent years, such as the BRG1 and FOXO3a in lymphoma, and SOCS1 in severe acute pancreatitis." (PMID 31992293, 2020). "MicroRNA-155 is known to target Socs1 and this combination of increased expression of miR-155 and suppression of Socs1 has been described in several B cell-derived lymphomas." (PMID 23496831, 2013). "SOCS1 is a known oncogene in many cancer types including lymphoma." (PMID 34282050, 2021). "We tested if the transcriptional levels of SOCS1 (the only regulator reported in the literature to be associated with inhibition of IL-10 signaling in a lymphoma cell line) and SOCS3 (as control; it does not inhibit IL-10R) were increased by IFN-β treatment." (PMID 30061883, 2018). "DNA hypermethylation of SOCS1 is also frequently found in certain types of lymphomas and in myelodysplastic syndrome, which may result in enhanced STAT1 and Jak2 activity and hence cell proliferation." (PMID 28445952, 2017). "Similarly, in the primary Karpas 1106P lymphoma cell line, a large biallelic chromosome deletion on 16p13.13 which includes SOCS1 was observed, again resulting in constitutive JAK-STAT signalling." (PMID 24757565, 2014). "Suppressor of cytokine signaling 1 (SOCS1) is frequently mutated in PMBL and other lymphomas." (PMID 23296022, 2013).
lymphoma (continued). "It is thought that impaired SOCS1-mediated JAK2 degradation results in sustained JAK2 activation and low turnover of JAK2 protein leading to lymphomas." (PMID 24757565, 2014). "Together, examination of four established expression signatures revealed that SOCS1 mutant cases and in particular SOCS1 major cases accumulate in GCB and PAP-1 lymphomas." (PMID 23296022, 2013). "In the context of lymphoma originating from the germinal center, such as PMBL, the SOCS1 gene is indeed a known target of the mutagenic enzyme activation-induced deaminase (AID), which initiates somatic hypermutation (SHM) by converting cytosine (C) to uracil (U) in single-stranded DNA." (PMID 37835560, 2023). "The COO signature divided the 24 SOCS1 mutant cases into 19 (79.2%) GCB-like lymphomas and 5 (20.8%) non-GCB lymphomas." (PMID 23296022, 2013).